INS (insulin)
Diseases named in the same sentence as INS in open-access papers (continued):
Sharing a sentence is not in itself a finding about the gene and the disease.
diabetes (continued). "Approximately 4-in-10 adult women in the US have been diagnosed with pre-diabetes or diabetes, an insulin-resistant condition that increases their propensity for developing sex-specific endocrinopathies (i.e., polycystic ovary syndrome), irregular menses, amenorrhea, and infertility." (PMID 39150916, 2024). "The resultant adipocytes were capable of facilitating insulin expression to alleviate diabetes." (PMID 38966749, 2024). "This affects insulin secretion and function which can lead to diabetes." (PMID 39011385, 2024). "While people without diabetes have been identified as an ‘at risk’ population from insulin-related hypoglyceamia, this was not demonstrated in this study." (PMID 38871123, 2024). "Even if we observe a delay in the onset of inflammation when considering insulin concentration as constant (see Section 4.2), it is clear that the relation between diabetes and insulin concentration could be improved." (PMID 38586183, 2024). "Insulin therapy serves as an injectable medication for diabetes mellitus." (PMID 39203828, 2024). "This compound showed anti-diabetic effects in rat, mouse, and zebrafish models of diabetes, including a decrease in blood glucose, glycosilated haemoglobin and lipid levels, preservation of pancreatic β-cells, increased insulin production, and glucose tolerance." (PMID 38786601, 2024). "As insulin prices have risen exponentially over the past 20 years, catastrophic spending, defined as using more than 40% of one’s income for medical supplies, has affected 14% of Americans with diabetes." (PMID 38344219, 2024). "Dysregulated insulin response due to defective VPS13B may explain the occurrence of diabetes in some CS patients." (PMID 38439002, 2024). "By mitigating the adverse effects of oxidative stress, glucotoxicity, lipotoxicity, and inflammation, polyphenols help preserve and enhance the insulin-secretory capacity of beta cells, which is essential for maintaining glucose homeostasis and preventing the progression of diabetes." (PMID 39594609, 2024). "Further, we believe the current group identified with postponed basal insulin-initiation, despite the potential exclusion of subjects referred to an outpatient diabetes clinic, still represents a clinically relevant sample of patients highly affected by therapeutic inertia." (PMID 38116986, 2024). "Additionally, smart insulin pens enhance diabetes care through dose tracking and real-time data sharing, improving accuracy and adherence." (PMID 39006724, 2024). "Besides testing for glucose, researchers can also diagnose and manage diabetes based on the concentrations of glycated hemoglobin (HbA1c or simply A1c) and insulin in the blood, as well as red blood cell (RBC) and neutrophil mechanics and behavior." (PMID 38509342, 2024). "Aglepristone serial administration (10 mg/kg, SC) on days 1, 2, 9, and 17 after the diabetes diagnosis in entire bitches in diestrus induced reduction in GH concentration and better glycemic control, allowing insulin dose reduction after two weeks of the beginning of the treatment." (PMID 38539988, 2024). "Many participants with diabetes had access to healthcare, and some of them might be using insulin, which could weaken the effect of BMI." (PMID 38791732, 2024). "Diabetes mellitus (DM) is a chronic metabolic disorder characterized by elevated blood glucose levels resulting from the body's inability to produce or effectively use insulin." (PMID 39229407, 2024). "Moreover, we have uncovered ApoA-I-SR-BI and ApoA-I-ABCA1 novel interaction pathway targets for improving insulin secretion to prevent and treat diabetes." (PMID 39546458, 2024). "The aetiology of DM is either related to autoimmune destruction of β-cell, usually leading to absolute insulin deficiency (type 1 diabetes), or a progressive loss of sufficient β-cell insulin secretion, usually on the background of insulin resistance (type 2 diabetes)." (PMID 38614881, 2024).
diabetes (continued). "Furthermore, Cinnamomum verum (cinnamon) was found in a meta-analysis to possibly improve fasting blood glucose levels and insulin sensitivity, underscoring its potential utility in managing diabetes." (PMID 39590851, 2024). "Conversely, selective B cell recognition of insulin can enhance diabetes in NOD mice." (PMID 38308004, 2024). "Moreover, GABA also improves glucose tolerance and insulin sensitivity, has immunomodulatory and anti-inflammatory effects, and ameliorates diabetes in different models." (PMID 39420751, 2024). "and combined lifelong insulin exposures are associated with decreased retinal arteriolar diameter in adulthood in a population without diabetes, even when adjusted for conventional cardiovascular risk factors." (PMID 39661465, 2024). "UCP-2, as a protein expressed in the adipose tissue and pancreatic endocrine system, could modulate insulin and glucose metabolism and regulate insulin secretion which could relate it to obesity and diabetes." (PMID 38678284, 2024). "However, the same authors reported that when they were inducing diabetes through streptozotocine there was an increase in the seric levels of insulin after the 8 weeks of both crude extract of Stevia rebaudiana and stevioside dosification." (PMID 38412182, 2024). "Together, these findings support that insulin therapy in treated diabetics enhances the regulatory cascade downstream of the insulin receptor to activate AKT and that could potentially rescue β-cell functionality." (PMID 39684905, 2024). "Consequently, many older people living with diabetes need to use insulin to avoid excessively high glucose levels." (PMID 38778253, 2024). "However, further research is necessary to confirm its effects on insulin sensitivity and resistance, which are crucial for managing diabetes-related complications." (PMID 39195171, 2024). "After adjusting for age, sex, APACHE II score, diabetes, use of glucocorticoid in hospital and use of insulin in hospital, only TARs with a glucose threshold of 10.5 mmol/l (190 mg/dl) or higher (TAR>10.5 to TAR>13.9) were significantly associated with in-hospital mortality risk." (PMID 38568252, 2024). "Furthermore, the convergence of wearable glucose monitors with automated insulin delivery systems represents a notable stride in diabetes management, facilitating continuous monitoring of blood glucose levels and responsive insulin administration." (PMID 38988886, 2024). "Such therapies could be aimed at enhancing insulin secretion in diabetes, protecting against liver and cardiac injuries, or improving reproductive health in conditions like obesity-induced infertility." (PMID 39398330, 2024). "We speculated that the putative mechanism may involve L-DOPA in MSM inhibiting pancreatic insulin secretion leading to hyperglycaemia and diabetes-like inflammation of the pancreas accompanied by elevated serum amylase and lipase." (PMID 39352513, 2024). "Because of these relations, it was suggested that apelin may act as an insulin-sensitizing agent and may be a potential target for the treatment of diabetes, given its effective activity in energy metabolism and insulin sensitivity improvement." (PMID 37930396, 2024). "For example, the guideline suggests a baseline HbA1c and a plasma glucose check before commencing anti‐cancer therapy or steroids, monitoring of random plasma glucose at each treatment visit, patient education, and collaborating with the diabetes team, for example, for support in titrating insulin." (PMID 39445809, 2024). "The influence of MI in this population may involve several complex signaling pathways in the diabetes–breast cancer link such as the insulin and insulin-like growth factor family of ligand receptors, dyslipidemia, adipose tissue, and the gut microbiome." (PMID 38982173, 2024). "However, as the disease advances, the body becomes unable to produce enough insulin to meet the demand, leading to hyperglycemia, frank diabetes, and ketosis." (PMID 38674910, 2024).
diabetes (continued). "Depending on the level of engagement and previous glycemic management, pregnancy may be the time a woman devotes the most effort to carbohydrate counting, SMBG, and interacting with diabetes devices such as insulin pumps and continuous glucose monitors." (PMID 38570742, 2024). "Hypoglycaemia is an acute complication of diabetes management that may occur as a consequence of insulin or insulin secretagogue therapy." (PMID 38795153, 2024). "Four single nucleotide polymorphisms (SNPs) of the KIF11 gene identified in the GWAS catalogue are associated with diabetes, including RS2153827, RS6583826, and RS7087591, which are all associated with the risk of T2DM, while RS7096101 is associated with insulin level." (PMID 38915894, 2024). "Sulfonylureas and insulin analogs, which are commonly used as second- and third-line therapies for diabetes, may lead to increased insulin-like growth factor levels and hence promote prostate cancer growth and simultaneously increase PSA levels." (PMID 38774165, 2024). "In addition, 39.9% of patients with diabetes were taking a biguanide, and 10.9% were under insulin therapy." (PMID 38932992, 2024). "Insulin resistance and decreased insulin production work together to create this type of diabetes." (PMID 38892571, 2024). "Diabetes primarily manifests itself as type 1 diabetes, in which an autoimmune process destroys insulin-secreting cells, and type 2 diabetes mellitus, characterized by the progressive destruction of islets due to functional alteration of insulin." (PMID 39273600, 2024). "Conventional use of insulin and oral medications is not effective in preventing the gradual loss of pancreatic beta cells in diabetes." (PMID 39062506, 2024). "It is a good source of cucurbitacins, cucumerin A and B, cucumegastigmanes I and II, and flavonoids such as vitexin, orientin, apigenin, and isoscoparin, which can synergistically improve plasma glucose, glycolysis, insulin sensitivity, and body weight in diabetes patients." (PMID 39519546, 2024). "About 8.4 million adults take insulin to treat their diabetes." (PMID 39458437, 2024). "Notably, after 7.5 h of incubation, there was about 100% insulin release under hyperglycemic conditions displayed by diabetes patients (3 mg mL−1)." (PMID 38167129, 2024). "Enhancing oral insulin delivery efficiency in diabetes treatment." (PMID 38675454, 2024). "Moreover, the exposure data excluded patients with diabetes, which raises the possibility of selection bias and collider bias, although insulin levels in patients with diabetes can also be affected by treatment and disease progression." (PMID 39210428, 2024). "Diabetes is closely related to insulin, a hormone secreted by the pancreas that regulates blood glucose balance, but type 2 diabetes can occur when there is insufficient insulin." (PMID 39065014, 2024). "In addition, the surges of growth hormone (GH) during puberty represent a great obstacle in managing diabetes at this stage of life because of the antagonistic relationship between the function of the GH and that of the insulin." (PMID 39203766, 2024). "In addition, HOMA-IR cannot estimate insulin resistance in patients with diabetes who are receiving insulin therapy." (PMID 38905235, 2024). "Approximately 12.1% (n=4) of patients with diagnosed diabetes received insulin." (PMID 38752177, 2024). "Additional studies are therefore needed to disclose how a diabetes nurse may affect the quality of insulin titration and intensification within a Norwegian general practice setting." (PMID 38116986, 2024). "Understanding how placental signals enhance insulin synthesis and secretion from β cells could be pivotal in developing new therapies for diabetes." (PMID 39432712, 2024). "The authors focus attention on the fact that the loss of chloride ions in tissues, which affects the pathogenesis of type II diabetes, may also be related to comorbidities in the course of diabetes, such as insulin sensitivity, myotonia, and kidney stones." (PMID 39796443, 2024).
diabetes (continued). "Patients with type 2 diabetes mellitus display elevated levels of tyrosine phosphatase 1B (PTPN1), and membrane IR-associated glycoprotein PC-1 (ENPP1), which downregulate IR phosphorylation and insulin signal transduction." (PMID 39199273, 2024). "However, we included potential confounding factors collected on the platform in our model, such as age, gender, diabetes type, diabetes duration, insulin treatment, and weight." (PMID 39257900, 2024). "Insufficient vitamin D levels may impair β-cell function and insulin action, contributing to poor diabetes control." (PMID 38741878, 2024). "This outcome suggests that the administration of insulin to individuals with diabetes does not appear to mitigate the loss of BMD." (PMID 38451994, 2024). "Individuals with diabetes reported treatment with Insulin in 4% or Metformin in 3%." (PMID 39103464, 2024). "In addition, novel insulin formulations, such as insulin glargine U-300, insulin degludec, insulin 287, oral insulin, and basal insulin peglispro, have been used to treat diabetes." (PMID 39234553, 2024). "We demonstrate that RFX6 haploinsufficiency does not affect beta cell number or insulin content but does impair function, predisposing heterozygous carriers of loss-of-function variants to diabetes." (PMID 38743124, 2024). "Moreover, the abnormally high concentration of plasma lipids in individuals with diabetes primarily results from the increased release of free fatty acids, a process in which insulin is necessary to inhibit hormone-sensitive lipase." (PMID 38926327, 2024). "In addition, glycated hemoglobin (HbA1c), insulin levels, and cellular biomechanics-related metrics have also been considered for microfluidic-based diabetes diagnosis." (PMID 38509342, 2024). "Additionally, advanced diabetes technology, such as continuous subcutaneous insulin infusion (CSII) and continuous glucose monitoring (CGM) devices, helps reduce hemoglobin A1c (HgbA1c) levels as well as hypoglycemia episodes." (PMID 40302971, 2024). "The main cause of diabetes, which is the lack of effective insulin, was correctly identified by 71.8% of the participants." (PMID 39160425, 2024). "Thus, individuals suffering from either type I or II diabetes demonstrate impairments in insulin secretion and/or poor glucose uptake that hinder the anabolic effects of insulin on skeletal muscle tissue." (PMID 38785544, 2024). "Elevated levels of IL-1β in diabetes activate the expression of other inflammatory cytokines and amplify the pro-inflammatory milieu, temporarily increase insulin secretion, which may be detrimental to metabolism." (PMID 38920850, 2024). "Therefore, these ILPs will provide a set of solutions to potentially solve a long-standing problem of designing truly monomeric, fast-acting insulin analogs for the treatment of diabetes." (PMID 38535452, 2024). "Their research suggested an interaction between insulin and melatonin in patients with diabetes." (PMID 39199338, 2024). "However, it is well understood by the transplant community that once they receive a kidney transplant and the requisite immunosuppression, the patient’s diabetes will worsen and ultimately require long-term insulin for control." (PMID 39364120, 2024). "In “brittle diabetes” and in GV, there is an important nutritional share, which, beyond the enormous advances in insulin pump therapy (CSII) and real-time interstitial glucose monitoring (CGM) with interconnected automated systems, also requires dietary supply." (PMID 39519472, 2024). "Our study discoveries can have profound impact on clinical practice: when the information about the duration of diabetes of patient is missing, medical doctors can use our tool and focus on age, insulin intake, and body-mass index to infer this important aspect." (PMID 38435625, 2024). "Diabetes mellitus type 1 is a chronic disease that implies mandatory external insulin delivery." (PMID 37715091, 2024).
diabetes (continued). "Inhibition of inceptor may be a new diabetes treatment that enhances insulin action in pancreatic β cells, and the development of inhibitors is expected." (PMID 39513056, 2024). "Swimming can help people with diabetes minimize oxidative stress by increasing insulin sensitivity." (PMID 38645750, 2024). "Interestingly, higher blood glucose levels after GS injection were observed in patients with type 1 diabetes mellitus (T1DM) and other types of diabetes treated with insulin." (PMID 39407860, 2024). "Insulin requirement must be assessed in patients who have long-term type 2 diabetes mellitus." (PMID 38654804, 2024). "Most European countries have an upper age limit and defer for health conditions such as insulin-treated diabetes, history of coronary artery disease or cancer, whereas other countries such as Canada and the United States do have no upper age limit and have less stringent health criteria." (PMID 38800670, 2024). "In addition, patients in the remission group had shorter estimated diabetes course, lower BMI, lower cholesterol and triglycerides, better blood glucose control, better islet function, and better insulin sensitivity 3 months after discharge." (PMID 38476668, 2024). "Besides, Diabetes mellitus (DM), a global epidemic that reveals itself when glucose levels in the blood rise too high and kidney function declines, is caused by a failure to create or properly utilize insulin." (PMID 39432502, 2024). "The etiology of diabetes is broad and complex, resulting from the interplay of environmental and genetic factors, and can be summarized as either impaired insulin secretion or insulin resistance." (PMID 39376538, 2024). "Being age advanced increased susceptibility with advancing age can be attributed to a decline in insulin sensitivity and alterations or insufficient compensation of beta-cell function in response to escalating insulin resistance, ultimately leading to diabetes." (PMID 39086906, 2024). "It is thought that this may be a result of increased nitric oxide (NO) pathway activity in diabetes, unrelated to insulin levels." (PMID 39289953, 2024). "In addition to diabetes and insulin, multiple significant dimension enlargements were seen in those diagnosed with hyperlipidemia and in those prescribed hypertension medications." (PMID 39006603, 2024). "Insulin is frequently used in the management of both type 1 and type 2 diabetes mellitus." (PMID 38594659, 2024). "Type 2 diabetes is a form of diabetes that can vary from primarily having a resistance to insulin (along with a relative lack of insulin) to primarily having abnormalities in insulin secretion (together with insulin resistance)." (PMID 38725826, 2024). "A large body of research, based on both clinical trials and meta-analysis, has evaluated the effectiveness of various diabetes medications, including insulin therapies, metformin, sulfonylureas, GLP-1 receptor agonists, SGLT2 inhibitors, DPP-4 inhibitors, and thiazolidinediones." (PMID 39583077, 2024). "Furthermore, in our previous study, we compared the efficacy of miR-10b mimic against diabetes in HFHSD-induced diabetic mice with antidiabetic medications [insulin, liraglutide, DPP-4 inhibitor (sitagliptin), and metformin]." (PMID 38396943, 2024). "Model 1 was adjusted for age, while Model 2 was adjusted for age, menopausal age, income, urban area, education, insulin usage, BMI, hypertension, diabetes mellitus, dyslipidemia, high alcohol intake, smoking, exercise, oral contraceptive use, and hormonal therapy usage." (PMID 38613076, 2024). "Within the subset of diabetes patients for which manual chart abstraction was performed, rates of medication use prior to hospitalization were as follows: insulin 50%, metformin 42%, DPP4 inhibitor 27%, sulfonylurea 14%, SGLT2 inhibitor 5.1% and GLP1 receptor agonist <1%." (PMID 39208154, 2024).